CDKN1A (cyclin dependent kinase inhibitor 1A)
Diseases named in the same sentence as CDKN1A in open-access papers (continued):
Sharing a sentence is not in itself a finding about the gene and the disease.
cancer (continued). "Despite the mixed results, several reports have explored the relationship between CDKN1A polymorphisms and cancer risks, although no definite conclusions have been reached." (PMID 37730565, 2023). "NRF2 can establish a positive feedback loop in CDKN1A-overexpressing cancers." (PMID 36765862, 2023). "CDKN1A is often down-regulated in human cancer cells and its up-regulated expression in our study could explain the IPA’s disease inhibition prediction." (PMID 36197921, 2022). "In addition to its role in the occurrence, progression and treatment of cancer, CDKN1A has also been proved to be related to muscle atrophy." (PMID 35847900, 2022). "Therefore, when assessing the role of CDKN1A-induced cell-cycle arrest in cancer cell sensitivity, the balance between DNA repair and proliferation inhibition should be considered." (PMID 35505963, 2022). "Only in N0, DNA (excision-) repair (involved genes: CDKN1A, PPM1D, and DDB2) was predicted to be a downstream function, while molecular networks in N2+ were associated with cancer, as well as injury and abnormalities (among others, downregulation of MSH6, CCNE2, and CHUK)." (PMID 36068491, 2022). "Finally, gene expression data from The Cancer Genome Atlas database (TCGA) revealed a strong correlation between the CDKN1A and SPINT2 expression levels in healthy samples, and a weak correlation in cancer samples in which SPINT2 is frequently mutated." (PMID 34962618, 2022). "Another study highlighted that EZH2 depletion may interfere with cancer cell proliferation both in vitro and in vivo via the induction of the p21/CDKN1A-mediated senescence." (PMID 34575678, 2021). "CDKN1A, as an oncogene, promotes cancer cell proliferation by inhibiting apoptosis." (PMID 34521875, 2021). "CDKN1A is a cyclin-dependent kinase inhibitor, and an important versatile cell cycle regulator that is involved in cell migration and autophagy and is often deregulated in various cancers." (PMID 33621203, 2021). "Furthermore, FLT1 of LUSC, ITGB1 of DLBC, MDM4, and CDKN1A of ACC, MAPK1, and ERBB3 of UCEC, FGFR1 of ESCA, and EREG and BCL2L1 of COAD have been strongly associated with patient survival in their respective cancers." (PMID 34079798, 2021). "It has been shown that Akt-related pathway could lead to resume DNA replication by recovery of genome stability, and drive cancer cells to M phase through stimulate expression of CDKN1A (cyclin-dependent kinase inhibitor 1A)." (PMID 34127725, 2021). "Therefore, the results of the present study suggest that EHMT1 plays a critical role in the regulation of cancer cell apoptosis and the cell cycle by modulating CDKN1A expression." (PMID 34214254, 2021). "Interestingly, heterologous vaccination also negatively regulated the expression of 35 genes including Cdkn1a and Msln which are involved in cancer progression." (PMID 34465781, 2021).
cancer (continued). "The top intracellular pathways of the 12 overlapping genes were associated with circadian rhythms and entrainment (Arntl, Cry2, Per2, Per3, Bhlhe41), the cell cycle (Cdkn1a, Wee1), the oxytocin signaling pathway (Cdkn1a, Rcan1), and transcriptional misregulation in cancer (Cdkn1a, Per2)." (PMID 33668521, 2021). "Likewise, CDKN1A up–regulation upon MSI1 depletion in P19 mouse embryonal carcinoma cells promoted neuronal differentiation, rescued by additional CDKN1A depletion." (PMID 34062997, 2021). "Further analysis of WES data revealed additional variants in common cancer‐related genes involved in DNA replication and DNA damage (e.g., ATM, CDKN1A), cell polarization (SCRIB), proliferation (RNASEL), VEGF expression (MAP3K1, MAP3K6), and in genes encoding growth factors (FGF2) (Table EV2)." (PMID 32667137, 2020). "CDKN1A plays a crucial role in regulating cell cycles to prevent cancer progression." (PMID 33133123, 2020). "In cancer, Cdkn1a is a well-characterized target of MYC–MIZ1 complexes." (PMID 32407433, 2020). "These genes contain known cancer-related genes such as Jak3, Foxo1, and Cdkn1a (p21)." (PMID 30621584, 2019). "Knockdown of Gls1 increased the expression of Cdkn1a and Cdkn1b and decreased the expression of some critical oncogenes for cancer cell survival, such as c-Myc, Cdk4, and NfκB, as well as some genes which are essential for MM cell survival, such as Irf4, Prdm1, Csnk1α1, and Rassf5." (PMID 31666930, 2019). "CDKN1A also plays a crucial role in various cancer development." (PMID 30706161, 2019). "To investigate cancer predisposition we generated cohorts of Cdkn1a-/- and Rb1G/G; Cdkn1a-/- mutants, as lack of cancer susceptibility of Cdkn1a knock out mice has only been reported for young mice." (PMID 30703085, 2019). "Another important locus that is epigenetically controlled in cancer by the activity of lncRNAs is that one encoding for the negative cell-cycle regulator CDKN1A (encoding the p21 tumor suppressor)." (PMID 29443889, 2018). "First, for the assessment of CDKN1A expression in CCA tissues, we carried out the analysis of the dataset GSE76297 (92 pairs of cancer and 91 normal tissue samples) and figured out that CDKN1A had lower expression in the cancer tissues in comparison with the typical tissues in CCA." (PMID 29970899, 2018). "This may suggest that the upregulation of sets of miRNAs in these cancers can synergistically downregulate CDKN1A." (PMID 30123182, 2018). "We hypothesize that chromatin regulation by HDACis, particularly at the CDKN1A gene, could sensitize cancer cells to photochemical and photobiological processes induced by HY-PDT." (PMID 28603560, 2017). "Although its mechanism and effect on cancer are still unknown, several reports have indicated that CDKN1A may be a biologic predictor and beneficial target for cancer treatment using cell cycle alteration." (PMID 25799222, 2015). "CDKN1A could be regulated by several miRNAs in many cancers, including miR-519d, miR-375, miR-31 and miR-663." (PMID 26582573, 2015). "CDKN1A (p21), a key inhibitor of the cell cycle, is also frequently dysfunctional in human cancer." (PMID 26238857, 2015). "Our data identify a new regulator of the cell-cycle inhibitor CDKN1A/p21 that acts as a proliferative factor in cancer cell lines and in glioblastomas and demonstrate that Alu elements present in lncRNAs can contribute to targeting regulatory lncRNAs to promoters." (PMID 24748121, 2014). "We suspected that FBI-1 might also play a role in establishing and maintaining epigenetically silent CDKN1A by DNA methylation in cancer cells." (PMID 23658227, 2013).
cancer (continued). "Epigenetic silencing of CDKN1A gene expression in cancer cells by histone modification and promoter DNA methylation is suggested by the upregulation of CDKN1A gene expression after treatment with the HDAC inhibitor trichostatin A (TSA) or the DNA methylation inhibitor 5-aza-2'-deoxycytidine." (PMID 23658227, 2013). "The cyclin-dependent kinase inhibitor CDKN1A (encoding p21WAF1/CIP1) is upregulated by vorinostat and other HDACIs in several cancer cell lines, an effect that correlates with cell cycle arrest and has been suggested to induce protection from cell death mediated by HDACIs." (PMID 22116303, 2012). "Future investigations may wish to focus on the transcriptional influence of CRY2 on oncogenic CCND1, and the relationship with CDKN1A, as these findings have the potential for broad impact on a number of cancer types." (PMID 20334671, 2010). "The up regulation of CDKN1A usually leads to the apoptosis of the cancer cells." (PMID 20459793, 2010). "Changes in the CDKN1A gene and its expression may have an important role in cancer pathogenesis, since its normal function comprises suspension of the cell cycle, terminal differentiation and apoptosis." (PMID 20169278, 2009). "However, interactions between angiogenesis (VEGFA) and cell cycle regulation (CDKN1A) may be plausible given their roles in processes like cancer, where dysregulation of both blood supply and cell proliferation is common." (PMID 41554049, 2026). "Indeed, there is direct evidence suggesting that CDKN1A may reduce the sensitivity of cancer cells to doxorubicin-induced cell death." (PMID 41345520, 2025). "If the damage has not been resolved or repaired, CDKN1A gene promotes apoptosis and cellular senescence to eliminate damaged cells that could potentially cause cancer." (PMID 39498386, 2024). "As to CDKN1A, which codes for the p21 tumor suppressor protein, we unexpectedly revealed lower methylation levels within the proximal promoter and 1st exon alike in carcinomas compared to BOTS, especially when BOTS without the BRAF V600E variant were considered." (PMID 39456618, 2024). "Among the 16 cell cycle‐associated genes analysed, only CDKN1A expression was increased more than 1.5‐fold in SRSF3‐depleted cells, suggesting that the cell proliferation and cell cycle phenotype in human cancer cells was largely mediated through miR‐17a/20a targeting CDKN1A." (PMID 37306233, 2023). "However, under certain unknown circumstances, CDKN1A can play a completely opposite role in promoting cancer growth." (PMID 36765862, 2023). "However, why these cells are sensitive to cisplatin remains unclear, although a recent study reported that CDKN1A upregulation reduced cancer cell sensitivity to cisplatin." (PMID 36139614, 2022). "In many cancer cell types, 1,25-(OH)2D3 directly arrests the cell cycle in the G0/G1 phase by downregulating cyclin-dependent kinases (CDKs: CDK4, CDK6) and repressing the genes that encode cyclins D1 and C (CCND1, CCNC) and CDK inhibitors p21CIP1/WAF1 (CDKN1A), p27KIP1 (CDKN1B) and p19 (CDKN2D)." (PMID 35406059, 2022).
cancer (continued). "Hence, different cancer-relevant alterations might contribute to downregulation of CDKN1A and thereby, possibly to CIN." (PMID 33168930, 2021). "However, the lack of cancer predisposition in Rb1G/G; Cdkn1a-/- mice suggests that these deficiencies aren’t cancer enabling on their own." (PMID 30703085, 2019). "Several studies have showed CDKN1A could mediate G1 cell cycle arrest in cancer cells." (PMID 29759079, 2018). "In addition, autophagy regulates the ROS-mediated induction of the cell cycle inhibitor CDKN1A/p21, which controls cellular proliferation, contributes to therapy resistance in cancer and controls phosphorylation of extracellular signal-regulated kinase MAPK1/ERK, which is a core regulator of p21." (PMID 28545464, 2017). "In the Cancer Cell Line Encyclopedia (CCLE) database, ATIC was found to be overexpressed, while CDKN1A, DNAJB9, EDEM1, and GABARAPL1 exhibited lower expression levels, aligning with the gene expression patterns observed in our model equations." (PMID 41040512, 2025). "It was shown that LNCaP cells had higher cyclin‐dependent kinase inhibitor 1A (CDKN1A) expression and lower 3‐phosphoinositide‐dependent kinase 1 (PDK1) expression, both of which have been connected to the development of cancer." (PMID 41179368, 2025). "The mRNA levels of CDKN1A, EMC2, FDFT1, HSPB, and MT1G, were analyzed comprehensively, and any correlations between the levels of mRNA of these five genes and pan-cancer prognosis were identified." (PMID 40432442, 2025). "CDKN1A, EMC2, FDFT1, HSPB1, and MT1G were assessed for their ability to serve as prognostic indicators in pan-cancer by utilizing the TCGA database." (PMID 40432442, 2025). "These included multitrait colocalization at 6 loci with a consistent direction of effect between CAD and cancer (ABO, PGAP3, ANGPTL4, SREBF1, HAUS6, and SYNJ2BP) and 7 with an opposing direction (CDKN1A, RGS19, CALCRL, SF3A3, LAMC1, MYO9B, and MIA3)." (PMID 40874306, 2025). "The expression of mRNA of CDKN1A, EMC2, FDFT1, HSPB1, and MT1G in the TCGA and GTEx datasets were evaluated through the analysis of pan-cancer." (PMID 40432442, 2025). "Under a variety of damaging conditions, SPUD has comparable abundance relative to CDKN1A full-length isoform, SPUD is detectable in normal tissues and cancer cells." (PMID 37870464, 2023). "SPUD has low abundance compared to CDKN1A full-length isoform under basal conditions; SPUD is localized in the cytoplasm, is stable, and induced in cancer and normal cells during DDR." (PMID 37870464, 2023). "Apart from cancers, NSUN2-mediated m5C can regulate adipogenesis by promoting CDKN1A mRNA export and translation." (PMID 36792587, 2023). "By inhibiting cytosolic CDKN1A/p21, UC2288 impacts its anti-apoptotic function, resulting in decreased viability across various cancer cell lines." (PMID 38139316, 2023). "Hypermethylation of the CDKN1A/p21 promoter and the binding of other regulatory proteins such as SOX2 and LMNB2 lead to increased cancer cell proliferation by silencing its expression." (PMID 38139316, 2023).
cancer (continued). "Many of these DEGs, including CGA, CDKN1A, FN1, CLIC3, and S100P, have been reported to play essential roles in cancer progression." (PMID 35521536, 2022). "HDAC4 repressed the expression of CDKN1A in human cancer cells, and silencing of HDAC4 induced CDKN1A expression and inhibited cancer cell growth in vitro and in an in vivo human GBM model." (PMID 36139696, 2022). "In other reports, nitric oxide donors have been shown to induce cancer cell death by upregulating the expression of RASSF1 and CDKN1A, activating caspase 8/3 and regulating anti-apoptotic BCL-2 family members." (PMID 35205790, 2022). "The genes involving cell cycle control, DNA replication, apoptosis, senescence and autophagy in cancer pathways including CDK4, E2F1, Bax, CDKN1A, GADD45A, FAS, GABARAPL2, and SQSTM were significantly upregulated." (PMID 34305605, 2021). "In the other two most prominent networks, the link to cancer is more indirect for the respective genes although the score of their relevance to CRC is basically identical to that of SMAD2/AKT and CDKN1A." (PMID 34288395, 2021). "related to proliferation and apoptosis of cancer cells and detected the changes of downstream target expression in CCA cells after further knockdown of AGAP2-AS1,including CDKN1A,ADNP2,SLC29A2 by qRT-PCR." (PMID 33522895, 2021). "In both RWPE and PNT1A (two immortalized non-cancer human prostate cell lines), the overexpression of ETV4 reduced the luciferase expression from the CDKN1A promoter." (PMID 32791988, 2020). "Located upstream of the CDKN1A promoter, PANDAR (Promoter of CDKN1A Antisense DNA Damage Activated RNA) is involved in cell proliferation, migration, invasion, and apoptosis of cancer cells and are widely overexpressed in solid tumors." (PMID 31653018, 2019). "e-CSCs show many features that would be characteristic of the cancer cell of origin, including the over-expression of p21-WAF (CDKN1A), a key marker of senescence." (PMID 30760648, 2019). "TEL oncogene was shown as TF of CDKN1A and BBC3 and is related to “transcriptional misregulation in cancer” pathway." (PMID 30706161, 2019). "Similar to earlier findings in mES and EC cells, we showed that TRIM71 mediates CDKN1A mRNA regulation and controls proliferation of HEK293 and HepG2 cancer cells." (PMID 31732746, 2019). "CD19, CDKN1A, and TLR4 have also been reported to influence therapeutic resistance or overall prognosis in cancer." (PMID 29342159, 2018). "We found alterations in DNA methylation related to age for 803 unique genes, most corresponding to coding genes known to be involved in cancer (e.g., TP73, CDKN1A and ESR1)." (PMID 29383109, 2017).